TUG1 (taurine up-regulated 1)
Diseases named in the same sentence as TUG1 in open-access papers (continued):
Sharing a sentence is not in itself a finding about the gene and the disease.
infarction (1 paper, 2022). A localised pathological necrosis of tissue resulting from obstruction of the blood supply usually by a thrombus, an embolus, or vascular torsion. "The in vivo MI model showed increased infarction, myocardial injury, ROS levels and pyroptosis, which were inhibited by TUG1 silencing." (PMID 35396503, 2022).
kidney cancer (1 paper, 2022). Primary or metastatic malignant neoplasm involving the kidney. "Similarly, previous studies have shown remarkable elevation of TUG1 expression in kidney cancer tissues and its association with shorter overall survival of patients with kidney cancer." (PMID 35193488, 2022).
liver cirrhosis (1 paper, 2020). "Significant correlations of TUG1 expression with the number of tumors (P = .007) and liver cirrhosis (P = .041) were seen." (PMID 34766130, 2020).
meningioma (1 paper, 2013). A generally slow growing tumor attached to the dura mater. "Similarly, Taurine up-regulated gene 1 (TUG1) exhibits higher expression levels in both benignB and atypical meningioma with respect benignA meningioma." (PMID 23840654, 2013).
metastasis (1 paper, 2022). The spread or migration of cancer cells from one part of the body (where they first appeared) to another. "The results showed that TUG1 expression was correlated with tumor size, tumor node metastasis (TNM) stage, and lymph node metastasis (LNM), not with the age and gender." (PMID 35508523, 2022).
multiple sclerosis (1 paper, 2020). A progressive autoimmune disorder affecting the central nervous system resulting in demyelination. "At the same time, reducing the expression of lnc-TUG1 can also suppress the production and release of various immune factors through the TUG1/miR-9-5p/NF-κB1/p50 axis, thus reducing the the inflammatory response of multiple sclerosis." (PMID 33194692, 2020).
Nephropathy (1 paper, 2025). A nonspecific term referring to disease or damage of the kidneys. "For example, lncRNA TUG1 (taurine upregulated gene 1) is downregulated in DN, leading to mitochondrial dysfunction in podocytes; transgenic overexpression of TUG1 in podocytes of diabetic mice preserved mitochondrial biogenesis via PGC-1α and protected against nephropathy." (PMID 41300780, 2025).
ovarian tumor (1 paper, 2021). "In an ovarian tumor xenograft mouse model, TUG1 promoted tumor growth by resisting the effect of paclitaxel, and downregulation of TUG1 decreased the tumor size and weight." (PMID 34660304, 2021).
pancreatic adenocarcinoma (1 paper, 2023). "A previous report identified hsa-miR-582-5p/TUG1 axis to be involved in pancreatic adenocarcinomas (PAAD)." (PMID 37869015, 2023).
periodontal diseases (1 paper, 2024). "This study suggests that TUG1 might be a potential therapeutic target for promoting bone regeneration in periodontal diseases." (PMID 39156986, 2024).
pneumonia (1 paper, 2020). An acute, acute and chronic, or chronic inflammation focally or diffusely affecting the lung parenchyma, caused by an infection in one or both of the lungs (by bacteria, viruses, fungi, or mycoplasma.). "Moreover, TUG1 is reported to alleviate LPS-evoked inflammatory response in pneumonia." (PMID 33194901, 2020).
psoriasis (1 paper, 2025). An autoimmune condition characterized by red, well-delineated plaques with silvery scales that are usually on the extensor surfaces and scalp. "The down-regulation of TUG-1 is associated with both up-regulation of miRNA-377 and down-regulation PPAR-γ, which may contribute to the inflammatory cascade responses and chronicity that characterize psoriasis." (PMID 40725409, 2025).
relapsing (1 paper, 2022). "TUG1 was, however, downregulated in peripheral blood mononuclear cells (PBMCs) from relapsing-remitting MS patients, according to another expression study." (PMID 36324503, 2022).
respiratory infection (1 paper, 2021). "Besides, expression levels of TUG1 have been negatively correlated with respiratory infection, serum creatinine, white blood cell, C-reactive protein, APACHE II score, and SOFA score." (PMID 34956235, 2021).
spinal cord ischemia (1 paper, 2021). Reduced blood flow to the spinal cord which is supplied by the anterior spinal artery and the paired posterior spinal arteries. "Declines in lncRNA taurine-upregulated gene 1 (TUG1) expression inhibited inflammatory response in rats with spinal cord ischemia reperfusion and SCI." (PMID 34517787, 2021).
squamous cell carcinoma (1 paper, 2014). A carcinoma arising from squamous epithelial cells. "The lncRNA taurine-upregulated gene 1 (TUG1) is down-regulated in over 80% of non-small cell lung cancers (NSCLC; squamous cell carcinoma, adenocarcinoma) compared to normal tissue which is positively correlated with tumor size and pathological stage." (PMID 25119862, 2014).
sterility (1 paper, 2020). "Based on these results, we investigated whether perturbations in sperm morphology could also contribute to the complete sterility observed in Tug1−/− males." (PMID 32894169, 2020).
teratozoospermia (1 paper, 2020). "Together, these results indicate that the sterility of Tug1−/− males arises from a combination of low sperm count (oligozoospermia) and abnormal sperm morphology (teratozoospermia)." (PMID 32894169, 2020). "Microarray profiling of sperm from sterile men (a condition called teratozoospermia) has significantly less TUG1 expression compared with sperm from fertile males." (PMID 32894169, 2020).
tumor (216 papers, 2014 to 2025). "TUG1 (Taurine Upregulated Gene 1) expression abnormalities are associated with enhanced tumor cell proliferation, migration, and invasion in multiple cancers." (PMID 39991629, 2025). "High expression of TUG1 by suppressing miR-542-3p was associated with tumor stage, lymph node metastasis, and histological differentiation of CRC patients." (PMID 36333703, 2022). "TUG1 has recently been proposed as an oncogene in several types of cancer., TUG1 is associated with large tumor size, advanced pathological stages, and distant metastasis." (PMID 36333703, 2022). "following investigation of the TUG1 expression levels in 120 CRC patients, high TUG1 expression was observed in tumor tissue which was closely associated with the poor survival time of the CRC patients." (PMID 36333703, 2022). "High expression of TUG1 has been implicated in clinicopathological features of CRC including advanced tumor stage along with reduced overall survival and disease-free survival." (PMID 36333703, 2022). "We observed that TUG1 was upregulated in PA tissues and was associated with invasion, knosp grade and tumor size." (PMID 34021124, 2021). "Analyses of the subsequent tumors demonstrated that silenced miR-582-3p caused a significantly increased tumor growth, including tumor volume and weight; however, knockdown of lncRNA TUG1 remarkably suppressed these effects." (PMID 34793263, 2021). "Implantation of OC cells with reduced miR-582-3p caused increased tumor growth, while lncRNA TUG1 knockdown suppressed tumor growth and relieved the impact of reduced miR-582-3p in vivo." (PMID 34793263, 2021). "As angiogenesis is one of the crucial factors that impacts upon tumor development and progression, it is of interest to note that the lncRNA TUG1 has been associated with permeability of the blood–tumor barrier." (PMID 32650527, 2020). "On the other hand, TUG1 low expression in NSCLC tumor tissues was associated with a high TNM stage and a poor patient outcome." (PMID 32438606, 2020). "In support, lower expression of TUG1 is associated with larger tumor size, advanced tumor lymph node metastasis (TNM) stage, and poorer OS in NSCLC patients." (PMID 31480503, 2019). "Q-PCR analysis showed that TYMS expression level was positively associated with TUG1 in clinical recurrent tumor samples." (PMID 31528224, 2019). "TUG1 was significantly upregulated in OS tissues and associated with tumour size, distant metastasis, TNM stage, and overall and recurrence-free survival, which further indicated poor prognosis." (PMID 30911001, 2019). "Further analysis revealed that the deregulated lncRNAs in ESCC included many well-known tumor-associated lncRNAs, such as H19, TUG1 and SOX2OT, which have been reported to contribute to tumorigenicity in other cancers." (PMID 28854977, 2017). "High expression of TUG1 was found in 100 cancerous tissues and associated with poor features such as tumor size, distant metastasis, and TNM (Tumor, Node, Metastasis) staging." (PMID 29657297, 2017). "Upregulation of TUG1 and an association with higher tumour stages in UC was reported in previous studies." (PMID 28430799, 2017). "From the pooled results, it found that high TUG1 expression was significantly associated with distant metastasis (DM) (OR = 4.22, 95% CI: 2.66–6.70, P < 0.001), and tumor differentiation (OR = 2.45, 95% CI: 1.28–4.70, P = 0.007)." (PMID 29029461, 2017). "Five studies with 511 patients declared the association between the TUG1 expression levels and number of cancer patients with lager tumor size." (PMID 28977959, 2017). "To further elucidate the association between low TUG1 expression and poor prognosis in a subgroup of patients, we investigated an extended set of TCGA tumour samples (provisional set, n = 408) that also contains a higher number of non-muscle-invasive cases." (PMID 28430799, 2017).
tumor (continued). "In the literature, there is also support for the association of lncRNAs with small RNAs; for example, lnc-TUG1 is known to regulate blood–tumour barrier permeability by targeting miR-144." (PMID 27958323, 2016). "Overall, we elucidated a new mechanism underlying how TUG1 regulates tumor immunity." (PMID 38981064, 2024). "Additionally, exosomal TUG1 enhanced the polarization of M2 tumor-associated macrophages, which increased the proliferation and metastasis of CHS." (PMID 40330150, 2024). "In patients, TUG1 expression levels were associated with tumor mass and metastasis." (PMID 36831169, 2023). "Interestingly, TUG1-deficient mice demonstrated high and low expressions of E-cadherin along with N-cadherin as tumor metastasis-correlated EMT markers exerting the TUG1/miR-153-1/KLF4 axis in in vivo EMT of CRC cells." (PMID 36333703, 2022). "Moreover, miR-145 has been reported to target the lncRNA taurine upregulated 1 (TUG1), a tumor oncogene associated with various human cancers." (PMID 36077665, 2022). "Furthermore, the high expression of TUG1 is significantly associated with late tumor stage, poor differentiation, more lymph node metastases, and distant metastasis of tumors." (PMID 33747256, 2021). "These documents suit well with our finding that TUG1 acted as a predictive role in tumor diagnosis and could be used as a diagnostic biomarker." (PMID 34021124, 2021). "Interestingly, TUG1 downregulation was significant in the tumor tissues of male donors only and was associated with Squamous Cell Carcinoma (SCC) and LUAD tumor subtypes." (PMID 32438606, 2020). "From the analysis results, the tumor stage was significantly increased in the high TUG1 expression group compared with that in the low TUG1 expression group, and the results demonstrated that a high expression of TUG1 significantly increased the risk of high tumor stage." (PMID 28977959, 2017). "Associated with chromatin-modifying complexes, TUG1 plays a role in gene regulation, including repression of genes involved in cell cycle regulation, and it has been extensively associated with diverse tumor types." (PMID 29657297, 2017). "TUG1-siRNA combined with PD-L1 antibody can effectively inhibit tumor growth, providing a new target and strategy for HCC immunotherapy." (PMID 40352941, 2025). "Although this study has revealed the critical role of lncRNA TUG1 in the anti-tumor effects of Artesunate, the specific molecular mechanisms remain incompletely elucidated." (PMID 40758729, 2025). "Taurine upregulated gene 1 (TUG1), one of the early identified lncRNAs that act as a tumor-promoting factor, plays significant roles in HCC development and progression." (PMID 40696822, 2025). "Knockdown of TUG1 can inhibit tumor growth and metastasis, increase the infiltration of CD8+ T cells and M1 macrophages in the tumor, and activate CD8+ T cells through PD-L1 while enhancing macrophage phagocytosis through CD47." (PMID 40352941, 2025). "The upregulation of TUG1 is common in HB tissues and cells, indicating its potentially important role in tumor occurrence and development." (PMID 41393242, 2025). "Our findings revealed that overexpression of lncRNA TUG1 promoted the proliferation of MCF-7 tumor cells, whereas Artesunate administration inhibited this proliferative effect." (PMID 40758729, 2025). "Knockdown of TUG1 can inhibit tumor growth and metastasis while increasing the infiltration of CD8+ T cells and M1 macrophages in tumors." (PMID 40352941, 2025). "Consistent within vitro studies,TUG1 expression is significantly increased in HCC tumor tissues, and patients with high expression ofTUG1 have a poor prognosis." (PMID 40696822, 2025). "Silencing TUG1 inhibits tumor growth and metastasis, enhances the infiltration of CD8+ T cells and M1 macrophages, and activates CD8+ T cells through PD-L1 while promoting macrophage phagocytosis via CD47." (PMID 40352941, 2025).
tumor (continued). "Knockdown of TUG1 promotes anti‐tumor immunity by restoring the activation of CD8+ T cells and improves phagocytosis of tumor cells by macrophages." (PMID 38981064, 2024). "As the interactions between PD‐L1 and PD‐1 can inhibit the effector functions of tumor‐infiltrating T cells, we further elucidated that the knockdown of Tug1 in tumor cells promoted the co‐cultivated CD8+ T cells to display stronger activation phenotypes." (PMID 38981064, 2024). "There, up-regulated TUG1 is able to sponge different miRNAs, thus increasing the expression of their oncogenic targets prompting cell proliferation, migration, angiogenesis, tumor growth, and metastasis." (PMID 38835012, 2024). "High levels of TUG1 in tumor tissue were shown to correlate with poor patient survival in an analysis of TUG1 expression in 120 CRC patients." (PMID 39339648, 2024). "As m6A modification in lncRNAs plays a critical role in tumor epigenetic regulation, we further analyzed the relevance of TUG1 and the m6A methyltransferase METTL3." (PMID 38981064, 2024). "To evaluate the role of Tug1 in the tumor growth of HCC, we performed an orthotopic mouse model of HCC with sh‐NC and sh‐Tug1 Hepa1‐6 cells." (PMID 38981064, 2024). "Knockdown of TUG1 inhibited tumor growth and metastasis, increased the infiltration of CD8+ T cells and M1‐like macrophages in tumors, promoted the activation of CD8+ T cells through PD‐L1, and improved the phagocytosis of macrophages through CD47." (PMID 38981064, 2024). "LncRNA TUG1 was observed to be upregulated in PA tissues and related with tumor invasion, knosp grade, and tumor size." (PMID 37904679, 2023). "Previous studies have proven that TUG1 acts as a proto-oncogene, allowing for the proliferation of tumor cells." (PMID 37736902, 2023). "Future studies should be aimed to identifying the role of TUG-1 and miR-186 within the confines of well-known tumor suppressor and metabolic pathways." (PMID 37646973, 2023). "A novel network of regulatory mechanisms mediated by TUG1 induces remodeling injury in preeclamptic spiral arteries, and it is also aberrantly expressed in a variety of tumors, affecting tumor cell proliferation and apoptosis." (PMID 37340458, 2023). "TUG1 and PD-L1 expression was markedly increased in the tumor samples compared to the paired normal tissue samples by qRT-PCR analysis." (PMID 37813900, 2023). "In vitro studies have shown that KD of taurine upregulated gene 1 (TUG1) leads to remarkable suppression of tumor-induced endothelial cell proliferation, migration, and angiogenesis." (PMID 37384249, 2023). "The effect of TUG1 on tumor immune escape was detected by coculture, and cell viability was detected with a CCK8 assay." (PMID 37813900, 2023). "Long non-coding RNA (lncRNA) TUG1 acts as a proto-oncogene, allowing the proliferation of tumor cells, and it has been related to inflammation." (PMID 37736902, 2023). "TUG1 is a known regulator of podocyte health, and it regulates blood–tumor barrier permeability by targeting miR-144." (PMID 37511572, 2023). "TUG1 was recently discovered to be expressed abnormally in some tumors, impacting the proliferation and apoptosis of tumor cells." (PMID 37340458, 2023). "LncRNA TUG1 was upregulated in BC and was relevant with the tumor stage, lymphatic metastasis, and prognosis of BC." (PMID 37786775, 2023). "Depletion of TUG1 leads to overabundant R-loops and enhanced RS, leading to substantial inhibition of tumor growth." (PMID 37607907, 2023). "The knockdown of TUG1 has been shown to reduce immunosuppression and inhibit tumor progression both in vitro and in vivo." (PMID 37760852, 2023). "Compared to the 32 search results of MCM3AP-AS1 plus Cancer in PubMed, 262 search results of TUG1 plus Cancer showed a clearer regulatory mechanism in tumor development." (PMID 35237695, 2022). "siRNA knockdown of TUG1 effectively led to tumor progression inhibition and immune response improvement in HCC cells both in vitro and in vivo." (PMID 35237695, 2022).